CD47 (CD47 molecule)
Diseases named in the same sentence as CD47 in open-access papers (continued):
Sharing a sentence is not in itself a finding about the gene and the disease.
ovarian tumor (12 papers, 2010 to 2025). "Using homologous recombination–proficient ovarian tumor cells, another recent study demonstrated that olaparib improved macrophage-associated phagocytosis of cancer cells, with synergy when used in combination with anti-CD47 antibodies." (PMID 39138571, 2024). "IgG1 and IgG4 anti-CD47 mAb secreted by oHSV-infected tumor cells blocked the CD47/Sirpα signaling pathway and enhanced the phagocytosis of ovarian tumor cells by macrophages." (PMID 38832992, 2024). "While thrombospondin-1 (TSP-1) was mentioned for the first time two decades ago when elevated TSP-1 mRNA levels were found within ovarian tumors, most efforts focused on disrupting CD47/SIRPα up to now, in the purpose of promoting cancer cell phagocytosis." (PMID 34638503, 2021). "CD47 is a cell surface antigen highly expressed in ovarian tumors that functions equally as a macrophage “don’t eat me” signal enabling malignant cells to escape cell phagocytosis and thus detection by the immune system, by interacting with macrophage’ surface signal-regulatory protein-α (SIRPα)." (PMID 35211124, 2022). "The experimental results suggested that we successfully constructed HER2 CAR-Ms and CD47 CAR-Ms and verified the targeted phagocytosis effect on ovarian tumor cells in vitro." (PMID 37740183, 2023). "Dual CAR T cells co-expressing TAG-72 and CD47-truncated CARs showed stronger cytotoxicity in vitro when compared to single-target CAR T cells, especially against ovarian tumor cells expressing low levels of TAG-72." (PMID 37274261, 2023). "CD47 was first identified as an ovarian tumour antigen, however there is no known functional association with either 19q12 partner." (PMID 20844748, 2010). "Given the predominance of CD47 positivity in advanced ovarian tumors at diagnosis, with a paucity of negative tumors, CD47 expression does not appear to be a discriminatory inclusion criterion, nor a tool for stratifying patients for anti-CD47 therapy." (PMID 39138571, 2024).
ischemia (11 papers, 2014 to 2026). A hypoperfusion of the BLOOD through an organ or tissue caused by a PATHOLOGIC CONSTRICTION or obstruction of its BLOOD VESSELS, or an absence of BLOOD CIRCULATION. "CD47-enriched EV inhibit dendritic cell activation and ameliorate hepatic ischemia-reperfusion injury via interaction with SIRPα/CD172α+ DCs." (PMID 36353645, 2022). "CD47 controls basal and ischemic blood flow, and ischemia is known to occur in left heart failure induced by cardiac remodeling." (PMID 31827695, 2019). "CD47 blockade with a monoclonal antibody was preclinically tested in animal models of ischemia resulted in improvement of angiogenesis and great increases in tissue survival." (PMID 28714932, 2017). "In animals, an intravenous TSP1 bolus impaired restoration of blood flow following short term (<1 h) ischemia and this was ameliorated by gene silencing of Nox1 or treatment with a CD47 antagonist antibody." (PMID 24772092, 2014). "In soft tissues and visceral organs TSP1 inhibits blood flow following ischemia reperfusion injury (IRI) while TSP1−/− and CD47−/− animals display enhanced blood flow following ischemia and IRI." (PMID 24772092, 2014). "Consequently, strategies that inhibit ADAM17-mediated shedding are more relevant for acute ischemia than strategies targeting CD47." (PMID 41590849, 2025). "In MI or ischemia, down-regulation of CD47 may have unpleasant sequela such as diminished apoptosis of inflammatory macrophages, which can result in elevated levels of proinflammatory cytokines." (PMID 28714932, 2017). "Therefore, many studies focused on targeting TSP-1:CD47 interaction, aiming for up-regulation of physiological angiogenesis to enhance post-ischemia recovery or to facilitate engraftment." (PMID 26046793, 2015). "This suggests that while inhibition of CD47 may improve callus vascularization, the deleterious effect of a global deletion on other aspects of healing, specifically stromal cell expansion, outweighs the positive effect this may present on healing in the context of ischemia." (PMID 38562718, 2024).
astrocytoma (10 papers, 2015 to 2024). "Unmethylated MGMT in astrocytomas and the overexpression of CD47 and TIGIT in ADG tissues are associated with a poor prognosis." (PMID 38404571, 2024). "High expression of CD47, TIGIT, and CD47/TIGIT was all associated with poor survival in ADG and GBM, whereas high expression of CD47 was associated with shorter OS in astrocytoma." (PMID 38404571, 2024). "CD47, also called integrin-associated protein (IAP) or MER6, is ubiquitously expressed in astrocytoma cells as different isoforms." (PMID 35135556, 2022). "Recently, we showed that activation of CD47 in two human astrocytoma cell lines, upregulated the expression of UHRF1 with subsequent downregulation of p16INK4A." (PMID 27839516, 2016). "Moreover, 4N1K-induced stimulation of CD47 signaling promotes proliferation of astrocytoma cells, which is attenuated by CD47 blockade." (PMID 39039207, 2024). "The activation of CD47 promotes the proliferation of U87 and U373 astrocytoma cells, and CD47 may interact with PLIC-1, affecting the activation of PI3K/Akt pathway to stimulate the growth of astrocytoma cells." (PMID 36358792, 2022). "However, in astrocytoma, CD47 was shown to induce proliferation through Akt phosphorylation." (PMID 34768921, 2021). "Our study showed that CD47 and TIGIT expression levels in GBM were significantly higher than in astrocytomas and oligodendrogliomas." (PMID 38404571, 2024). "The expression of CD47 in GBM was higher than that in astrocytoma and oligodendroglioma (P = 0.004) and was higher in astrocytoma grade 4 than that in grade 2 or 3 (P = 0.006)." (PMID 38404571, 2024). "Dual CD47/TIGIT high expression was not correlated with age, sex, astrocytoma of all grades, or pTERT mutations." (PMID 38404571, 2024). "CD47 levels were higher in GBM and grade 4 astrocytoma tissues." (PMID 38404571, 2024). "High CD47 expression, but not TIGIT and CD47/TIGIT, significantly reduced the OS of patients with astrocytoma (P < 0.05)." (PMID 38404571, 2024). "Recently, we showed that CD47 activation using 4 N1 (CD47 agonist) peptide induced a significant increase in the expression of both UHRF1 gene and protein in human astrocytoma cell lines U87 and CCF-STTG1 (Grade IV) without affecting their expression in normal human astrocytes NHA." (PMID 27839516, 2016).
COVID-19 (10 papers, 2020 to 2025). A disease caused by infection with severe acute respiratory syndrome coronavirus 2. "Here, we concentrate on the role of the CD47 signaling pathway as a novel therapeutic strategy for COVID-19-associated cancer treatment." (PMID 37456027, 2023). "Eight of these articles contained information that supports a link between age-related increased CD47 levels and an elevated risk of severe COVID-19." (PMID 34698067, 2021). "Moreover, elevated SIRP-α expression was recently reported in blood mononuclear cells of COVID-19 patients, and the CD47/SIRP-α interaction was associated with lung damage in severe COVID-19." (PMID 34698067, 2021). "Finally, anti-CD47 antibodies reversed fibrosis in various organs in mouse models, which may be relevant in the context of COVID-19-associated pulmonary fibrosis." (PMID 34698067, 2021). "These cell adhesion molecules (ANXA1 and ICMA2), cytokine binding and receptor activity genes (CD44, CD45, CD47, CD74, and THBS1), and inflammatory genes (FPR1 and SELL) have been reported to be associated with COVID-19." (PMID 35172892, 2022). "In average, 32% (± 13%) of neutrophils from COVID-19 patients expressed CD47 in comparison to 25% (± 15%) in healthy donors (p < 0.05)." (PMID 35705573, 2022). "We have recently shown that blood neutrophils isolated from patients in the COVID-19 group have a higher surface expression of the “don’t eat me” signal CD47, which prevents phagocytosis and prolongs survival." (PMID 36466824, 2022). "Further research will be needed to define the roles of CD47 and/or SIRPalpha in COVID-19 in more detail." (PMID 34698067, 2021). "Further research will be needed to investigate the potential involvement of CD47 and SIRPalpha in COVID-19 pathology." (PMID 34698067, 2021). "Here, we investigated the potential role of the ubiquitously expressed cell surface glycoprotein CD47 in severe COVID-19." (PMID 34698067, 2021). "Thus, high CD47 levels may predispose these groups to severe COVID-19." (PMID 34698067, 2021). "Thus, we performed an in-silico study to investigate the role of CD47/SIRP in the severity of COVID-19 and as a potential target in critical cases." (PMID 41184328, 2025). "Moreover, we found that IL-8 and IL-26 display comparable correlations with CD47, a marker of neutrophil prolonged survival, in the COVID-19 group." (PMID 36466824, 2022). "Importantly, neutrophil scRNA-seq profile for CD47, the "don’t eat me signal” is minimal, with only 0.3–0.91% of neutrophils with > 2 × fold CD47 (n = 19 COVID-19 patients)." (PMID 35379853, 2022). "Interestingly, among the cytokines investigated, only IL-26 (r = 0.40) and IL-8 (r = 0.49) displayed a positive correlation with CD47 expression in blood neutrophils from the COVID-19 group." (PMID 36466824, 2022). "Moreover, the increase in blood IL-26 correlates with enhanced surface expression of the “don’t eat me” signal CD47 on blood neutrophils isolated from patients with acute COVID-19." (PMID 36466824, 2022). "Here, we investigated a potential role of CD47 expression in determining COVID-19 severity." (PMID 34698067, 2021). "The results indicated an ageing-related increase in CD47 expression, which may contribute to the increased COVID-19 vulnerability in older patients." (PMID 34698067, 2021). "Thus, we may suggest that a combination of ASNase and the selected small-molecule drugs that target critical residues in CD47/SIRP prevents stroke in critical cases of COVID-19 via interference with their binding." (PMID 41184328, 2025). "Hence, age-related and virus-induced CD47 expression is a candidate mechanism potentially contributing to severe COVID-19, as well as a therapeutic target, which may be addressed by antibodies and small molecules." (PMID 34698067, 2021).
COVID-19 (continued). "High CD47 levels contribute to vascular disease, vasoconstriction, and hypertension, conditions that may predispose SARS-CoV-2-infected individuals to COVID-19-related complications such as pulmonary hypertension, lung fibrosis, myocardial injury, stroke, and acute kidney injury." (PMID 34698067, 2021). "Therefore, high CD47 and/or SIRPα levels may affect initial virus control resulting in enhanced virus levels, which may eventually lead to the hyperinflammation and immunopathology observed in severe COVID-19." (PMID 34698067, 2021). "While CD47 efficacy in infectious diseases, especially severe COVID-19 studies, is lacking, focus on macrophage-mediated immunotherapy that increases "eat me" signals in combination therapy with mAbs is optimistic." (PMID 37456027, 2023). "The plasma concentration of TNFα correlated with the surface expression of CD47 when the COVID-19 and Control groups were pooled for analysis, whereas the concentration of IL-6 in plasma did not correlate with CD47 expression in any group." (PMID 36466824, 2022). "High expression of CD47 (“don’t eat me” marker) has not been shown before in patients with COVID-19." (PMID 35705573, 2022).
esophageal squamous cell carcinoma (10 papers, 2019 to 2026). Esophageal squamous cell carcinoma (ESCC) is a type of esophageal carcinoma (EC) that can affect any part of the esophagus, but is usually located in the upper or middle third. "In mice models with esophageal squamous cell cancer, treatment with anti-CD47 antibodies led to an increase in PD-1 and CTLA-4 expression." (PMID 34944850, 2021). "CD47 is overexpressed in the tumor tissues of esophageal squamous cell cancer (ESCC) patients." (PMID 32811852, 2020). "In esophageal squamous cell carcinoma, anti-CD47 treatment has shown promising results in vitro." (PMID 32811852, 2020). "When investigating esophageal squamous cell carcinoma (ESCC), researchers found an increase in both PD-1/PD-L1 expression and CD47 expression." (PMID 38261139, 2024). "Based on the existing evidence, the “don’t eat me” signal CD47 has been reported to exhibit elevated levels of CSCs from liver cancer, pancreatic cancer, esophageal squamous cell carcinoma (ESCC), lung cancer and other cancer types." (PMID 36910604, 2023). "We aimed to explore the prognostic effects of CD47/CD133 and the potential therapeutic significance of CD47 in esophageal squamous cell carcinoma (ESCC)." (PMID 30741466, 2019). "For example, Tao and colleagues assessed tumor samples from esophageal squamous cell cancer patients, showing an inverse relationship between CD8 T cell density and CD47 expression." (PMID 34944850, 2021). "Consequently, the development of anti-CD47 antibodies is warranted, and anti-CD47 therapy has been shown to enhance the efficacy of PD-1 and CTLA-4 inhibitors in esophageal squamous cell carcinoma (ESCC)." (PMID 40963868, 2025).
myeloid malignancies (10 papers, 2019 to 2025). "Upregulation of immune inhibitory checkpoints PD1, CTLA4, and CD47 has been consistently documented in myeloid neoplasms driving many prior clinical trials of antibodies aimed at blocking these proteins in patients with MDS and AML." (PMID 40111422, 2025). "Magrolimab is a first-in-class anti-CD47 monoclonal antibody that has been investigated for the treatment of myeloid neoplasms." (PMID 39199554, 2024). "CD47/SIRPα axis-targeting agents are promising additions to the current therapeutic armamentarium in myeloid malignancies." (PMID 35883692, 2022). "CD47 was shown to be overexpressed in myeloid malignancies, leading to tumor evasion of phagocytosis by macrophages, and blockade of CD47 leads to engulfment of leukemic cells and therapeutic elimination." (PMID 33757574, 2021). "This review will describe the role of CD47 in myeloid malignancies and pre-clinical data supporting CD47 targeting." (PMID 32038992, 2019). "Prophagocytic signals such as CD47 on AML cells can be induced by cell damage after treatment with chemotherapy or epigenetic drugs avoid phagocytosis, and magrolimab, an anti-CD47 antibody has been under investigation in the treatment of myeloid malignancies after chemotherapy." (PMID 37808081, 2023). "While the clinical data of such agents in myeloid malignancies has been limited, initial data with magrolimab, a first-in-class anti-CD47 antibody, has been shown to be well-tolerated with encouraging efficacy results when combined with azacitidine in AML and MDS patients." (PMID 32038992, 2019). "The ICIs investigated in myeloid malignancies include those targeting T-cell checkpoints PD-1, PD-L1, and CTLA-4, as well as the macrophage checkpoint CD47." (PMID 39199554, 2024). "Recently, CD47 has been identified as a “do-not-eat-me” signal, which is overexpressed in myeloid malignancies." (PMID 34990402, 2022). "In addition to the T-cell immune checkpoints, CD47 is the dominant MΦ checkpoint, which is overexpressed in myeloid malignancies and inhibits phagocytosis through “do not eat me” signals upon its binding to SIRPα on MΦs." (PMID 34771453, 2021).
pulmonary hypertension (10 papers, 2014 to 2025). Increased pressure within the pulmonary circulation due to lung or heart disorder. "Supporting the role of CD47, the authors further demonstrated that hereditary CD47 deficiency reduced SCD-associated pulmonary hypertension due to a reduction in ROS levels." (PMID 38891066, 2024). "Moreover, the IF of lung sections from patients with SCD-associated pulmonary hypertension also revealed increased levels of CD47." (PMID 38891066, 2024). "Transgenic SCD (Berk) mice were found to spontaneously develop pulmonary hypertension and right ventricular hypertrophy, and CD47-null mice transplanted with Berk marrow had decreased congestion of RBC due to limited TSP1 signalling." (PMID 33920030, 2021). "In agreement, CD47 was upregulated in clinical pulmonary hypertension and contributed to pulmonary arterial vasculopathy and dysfunction in mouse models." (PMID 34698067, 2021). "Increased CD47 levels were also detected in the lungs of a sickle cell disease patient with pulmonary arterial hypertension, and vasculopathy and pulmonary hypertension were reduced in a CD47-null mouse model of sickle cell disease." (PMID 34698067, 2021). "Interestingly, in the lungs of Berkeley SCD mice and SCD-associated pulmonary hypertension patients, TSP1 and CD47 were elevated." (PMID 38891066, 2024). "TSP and CD47 were upregulated in SCD patients with pulmonary hypertension (PH) in their conditions and they hypothesized the TSP–CD47 signaling promotes PH, in part, by increasing reactive oxygen species (ROS)." (PMID 34208829, 2021). "TSP1 and CD47 expression was elevated in the pulmonary tissue of SCD mice and humans with pulmonary hypertension." (PMID 33920030, 2021). "The activation of CD47, via TSP1, stimulates the interaction of endothelin-1 (ET-1) with endothelin receptor A, mediating proliferation and hypertrophy of pulmonary arterial smooth muscle cells as well as vasoconstriction, leading to pulmonary hypertension." (PMID 33920030, 2021). "Likewise, interrupting matricellular activation of CD47 enhances liver and kidney survival following IRI and ablates pulmonary arterial hypertension in rodents." (PMID 24772092, 2014).